MTOR (mechanistic target of rapamycin kinase)
Diseases named in the same sentence as MTOR in open-access papers (continued):
Sharing a sentence is not in itself a finding about the gene and the disease.
heart failure (97 papers, 2013 to 2026). Inability of the heart to pump blood at an adequate rate to meet tissue metabolic requirements. "Dysregulation of the mTOR pathway has been implicated in various cardiovascular diseases, including heart failure." (PMID 41195005, 2025). "Dysregulated mTOR activity has been implicated in the pathogenesis of heart failure with both reduced and preserved ejection fraction (HFrEF and HFpEF)." (PMID 40734978, 2025). "IGF1Rtg causes increased IGF1R signalling, leading to elevated mTOR activity and autophagy inhibition, as well as age-associated heart failure, which can be overridden by SPD42." (PMID 39117797, 2024). "In summary, heart failure and cardiac hypertrophy is associated with activation of the mTOR signaling pathway, which can be modulated by reduced PGI activity." (PMID 37938421, 2023). "Previous studies have shown that metabolic and structural remodeling is a hallmark of heart failure and that this remodeling involves the activation of the mTOR signaling pathway." (PMID 37938421, 2023). "Patients suffering from heart failure and experimental animals with diastolic dysfunction differ in the triggering of mTOR and the linked S6K1 signaling mechanism." (PMID 35163076, 2022). "In this regard, the dysregulation of mTOR signaling has been linked to many age-related pathologies, including heart failure and age-related cardiac dysfunction." (PMID 33513917, 2021). "MiR-221 acts as an important regulator of autophagy balance and cardiac remodeling by modulating the p27/CDK2/mTOR axis, and miR-221 has been implicated as a therapeutic target in heart failure." (PMID 32477928, 2020). "Overexpression of miR-221 has been shown to cause cardiac dysfunction and heart failure accompanied with impaired autophagy through the targeted repression of p27, a cyclin-dependent kinase inhibitor, and subsequent mammalian target of rapamycin (mTOR) activation." (PMID 29290979, 2017). "mTOR is influenced byvarious factors, including nutrient availability and cellular stress, which canfurther complicate its role in heart failure." (PMID 40776946, 2025). "Here, we report the effectiveness of an mTOR inhibitor in treating a fetus with large rhabdomyomas exhibiting severe heart failure when administered transplacentally." (PMID 40490815, 2025). "In heart failure, mTOR signaling also plays a pivotal role in the transition from compensatory hypertrophy to decompensated heart failure." (PMID 40734978, 2025). "For example, the acetylation status of mTOR targets can alter energy metabolism and redox balance during heart failure, while deacetylation therapies targeting the SIRT1-mTOR axis have shown potential in alleviating diabetic cardiomyopathy." (PMID 40734978, 2025). "Under normal physiological conditions, mTOR promotesprotein synthesis and inhibits autophagy, thereby promoting cellular growth.However, in heart failure, mTOR activity can become dysregulated, leading toexcessive autophagy or apoptosis." (PMID 40776946, 2025). "In studies on rats, miR-17-5p has been identified as a key factor promoting pathological myocardial hypertrophy, inhibiting Mfn2 expression, activating the PI3K/AKT/mTOR pathway, and inhibiting autophagy, which leads to heart failure." (PMID 38892295, 2024). "GS can exert a coordinated anti-heart failure effect with metoprolol through the PI3K/Akt/mTOR pathway-mediated autophagy inhibition." (PMID 39141645, 2024). "Studies indicate tanshinone IIA protects cardiomyocytes and guards against heart failure after myocardial infarction, by activating the AMPKs/mTOR-dependent autophagy pathway." (PMID 39861845, 2024). "The upregulation of SIRT1, PGC-1α, and AMPK, along with inhibition of the Akt/mTOR pathway, promotes autophagy, diminishes myocardial hypertrophy, and improves heart failure." (PMID 37754811, 2023). "Insufficient autophagy during heart failure is associated with impaired SIRT1/PGC-1α and AMPK signaling, as well as the activation of the Akt/mTOR pathway." (PMID 37754811, 2023).
heart failure (continued). "AMPK can promote autophagy by activating mammalian target of rapamycin (mTOR) C1 and activate mTORC2 to avoid excessive autophagy activity, which is contrary to each other to delay the process of heart failure." (PMID 35811741, 2022). "Trehalose, just as rapamycin, regulates the balance between cardiomyocyte apoptosis and autophagy in heart failure by inhibiting mTOR signaling." (PMID 35330193, 2022). "In this regard, it was shown that excessive activation of mTOR/p70S6K exacerbates pathological hypertrophy and heart failure in AMPKα2 knockout mice." (PMID 35592411, 2022). "Here, our results showed that not only the phosphorylation of mTOR but also its downstream proteins p70S6K and 4EBP1 increased in pressure overload-induced heart failure." (PMID 34007292, 2021). "In this study, p-Akt/Akt and p-mTOR/mTOR slightly decreased in mice with heart failure compared with control group, indicating the synthesis of skeletal muscle protein in mice with heart failure tends to decline." (PMID 35126176, 2021). "Eventually, this results in cardiomyocyte hypertrophy mediated by mTOR signaling and increased heart failure markers." (PMID 33802976, 2021). "The activation of the mTOR signaling pathways is reported to have a cardioprotective effect against MI or other cardiac injury-induced cardiac dysfunction or heart failure via the promotion of autophagy, which is important for cardiac energy homeostasis." (PMID 33829047, 2021). "Moxibustion can protect cardiac function in rats with heart failure, possibly inhibiting excessive autophagy of cardiomyocytes and reducing inflammatory reactions through the elevation of mTOR expression." (PMID 33603819, 2021). "Here, the authors show that hexosamine biosynthetic pathway is elevated in the heart by pressure overload, which contributes to heart failure by persistent activation of mTOR." (PMID 32286306, 2020). "Its deletion is harmful as mTOR-knockout mice show heart failure, abnormal cell cycle progression in neurons, and inhibition of embryonic stem cell development." (PMID 33597876, 2020). "This study aimed to investigate the effect of typhaneoside on ventricular remodeling and regulation of the PI3K/Akt/mTOR autophagy transduction pathway in rats with heart failure after myocardial infarction." (PMID 31201434, 2020). "Our data reveal that chronic upregulation of the HBP and consequent O-GlcNAcylation in the heart leads to persistent activation of mTOR, exacerbated pathological cardiac remodeling, and heart failure." (PMID 32286306, 2020). "In the model of heart failure, cardiac-specific overexpression of miR-221 significantly deteriorates cardiac function and promotes heart failure and mTOR axis-related autophagy." (PMID 33392270, 2020). "Previous studies have revealed that miR-221 inhibits autophagy and promotes heart failure by modulating the p27/CDK2/mTOR axis and inhibits hypoxia/reoxygenation-induced autophagy through the DDIT4/mTORC1 and TP53INP1/p62 pathways." (PMID 32477928, 2020). "Lastly, it was shown that reduction of mTOR signaling in adult mice induces the development of heart failure due to the accumulation of dephosphorylated 4E-BP1." (PMID 32722591, 2020). "The mTOR and its downstream signaling pathways are key regulators of autophagy and involved in pathological cardiac remodeling and even heart failure." (PMID 29872406, 2018). "Complete genomic deletion of mTOR resulted in a fatal, dilated-heart phenotype and even partial loss of mTOR activity impaired hypertrophic cardiac growth and accelerated heart failure development, implicating role of mTOR in cardiac homeostasis." (PMID 25880554, 2015). "Pharmacologic mTOR inhibition by rapamycin attenuated adverse cardiac remodeling and dysfunction in experimental heart failure (HF)." (PMID 24312548, 2013). "mTOR's role in myocardial infarction (MI) and heart failure is similarly complex." (PMID 40734978, 2025).
heart failure (continued). "While mTOR activation can initially promote hypertrophic responses in the myocardium as an adaptive mechanism to stress, prolonged activation contributes to pathological remodeling, including ventricular dilation and heart failure." (PMID 40734978, 2025). "mTOR signaling pathway is one of the effective ways to treat heart failure." (PMID 37426419, 2023). "(2021) found that moxibustion could protect the heart function of rats with heart failure by regulating autophagy through the mTOR signaling pathway." (PMID 35315239, 2022). "Interestingly, the genetic or pharmacological inhibition of mTOR can also prevent cardiac diseases, including cardiac remodeling and heart failure, in response to pressure overload and chronic myocardial infarction." (PMID 35190965, 2022). "In the mouse model of left ventricular hypertrophy induced by coarctation of the aorta, inhibiting PI3K/Akt-mTOR expression could prevent the development of left ventricular hypertrophy and cardiac insufficiency." (PMID 33582656, 2021). "This review will focus on the role of mammalian target of rapamycin (mTOR) signaling in cardiac aging and heart failure, including the signaling network and potential treatments targeting the mTOR complex 1 pathway in aging and heart failure." (PMID 33513917, 2021). "Inhibiting mTOR and NF-κB may improve the contractility of the heart, abolish the angiotensin II-induced hypertrophic response of cardiomyocytes, and prevent heart failure." (PMID 32775437, 2020). "This suggests that modulation of cardiac mTOR signaling by HDL could represent a novel therapeutic strategy for heart failure." (PMID 28904868, 2017). "Modulation of cardiac PI3K/mTOR signaling by HDL could represent a novel therapeutic strategy for heart failure." (PMID 28904868, 2017). "Ablation of mTOR in cardiac myocytes rapidly induces heart failure (HF) in adult mice." (PMID 26306297, 2015). "Genetic ablation of mTOR results in myocyte apoptosis and cardiac failure." (PMID 24628978, 2014). "Additionally, the overexpression of cardiac mTOR protects against I/R injury-induced heart failure and sufficiently enhances both mortality and function." (PMID 25549249, 2014). "Therefore small molecule inhibitors and FDA approved mTOR inhibitors targeting mTORC1-S6K1 might be an interesting target for further heart failure therapy." (PMID 41327199, 2025). "In addition, elevated leucine levels may activate mTOR, and inhibition of mTOR in a heart failure model improves cardiac function." (PMID 37426419, 2023). "Finally, we showed that mTOR inhibition prevented functional dysregulation in vitro, and that, using this information, mTOR inhibition led to a remarkable improvement in clinical status in a patient with the LMNA E161K mutation and severe heart failure." (PMID 35887646, 2022). "Suppression of the protein kinase B (PKB), also known as Akt, mammalian target of rapamycin (mTOR) pathway (Akt-mTOR pathway) using a proprietary IH exposure device induces autophagy in rat myocardium, and blocking this induction with an inhibitor has been reported to lead to heart failure." (PMID 36438601, 2022). "Therefore, on the basis of antihypertensive therapy, mTOR inhibitors may provide a new therapeutic candidate for delaying myocardial remodeling and cardiac insufficiency in postmenopausal hypertensive women." (PMID 34874016, 2022). "Thus, our study demonstrated that WXKL could reverse heart failure by regulating mTOR activity and autophagy and provided further evidence that an appropriate level of autophagy is essential for the maintenance of cardiac function." (PMID 28713489, 2017). "Fu and colleagues have discovered that PAGln promotes cardiac inflammation and fibrosis in mice, thereby increasing the incidence of ventricular arrhythmias in mice with heart failure, through the activation of the TLR4/AKT/mTOR signaling pathway." (PMID 40135235, 2025).
heart failure (continued). "In fact, when both mTOR and 4E-BP1 are deleted, heart failure phenotypes are improved due to unrestricted availability of eIF4E." (PMID 32722591, 2020). "Since mTOR is sensitive to the availability of nutrients, and DCM that evolves to heart failure is characterized by a pathologic alteration of cardiac metabolism, we analyzed the metabolome of normal and DCM hearts." (PMID 31546610, 2019). "Our current study demonstrated that some compounds from SFQX can bind to the protein kinase domain of mTOR, which indicated that SFQX may help the intervention of cardiac aging and heart failure." (PMID 38481330, 2024). "Earlier studies have described heart failure in mouse models following embryonic or perinatal deletion of essential proteins involved in the IR/IGF1R signaling pathway, i.e., IR/IGF1R, IRS1/2 (13, –, 15), and mTOR." (PMID 36125265, 2022). "The expression of XBP1s was decreased in the heart tissue of both human and rodents with heart failure, heart-specific XBP1 overexpression prevented the development of cardiac dysfunction, and XBP1s stimulated adaptive heart growth by activating mammalian target of rapamycin (mTOR) signal." (PMID 35321102, 2022). "Both mTOR and TGF-β1/Smad pathways have been shown to be activated by Ang-II in heart failure." (PMID 34007292, 2021). "MTOR, EP300 and PPP3CC in the Senescence Pathway were also involved in failure of heart." (PMID 32423033, 2020). "However, some studies have shown that upregulation of autophagy may protect cardiomyocytes through AMPK, mTOR, or FOXO signaling pathways, promote mitochondrial clearance, inhibit cell death, slow down heart failure, and reduce myocardial injury." (PMID 35588578, 2022). "Suppression of autophagy by activating mTOR signaling did not prevent heart failure." (PMID 36125265, 2022). "Thus, the QC-mediated inhibition of mTOR and TGF-β1/Smad pathways may account for improvement of heart function in the pressure overload-induced model of heart failure." (PMID 34007292, 2021). "Thus, the possibility that mTOR was activated as a result of increased autophagy in the heart failure can’t be rule out." (PMID 31277657, 2019). "Cardiac-specific knockout of mTOR showed an impaired hypertrophic response and enhanced heart failure progression after TAC mediated pressure-overload in mice, suggesting detrimental effects when mTOR is lacking." (PMID 29527175, 2018).
osteoarthritis (97 papers, 2015 to 2026). A noninflammatory degenerative joint disease occurring chiefly in older persons, characterized by degeneration of the articular cartilage, hypertrophy of bone at the margins and changes in the synovial membrane. "Aberrant mTOR signaling has been associated with mitochondrial impairment and cartilage breakdown in osteoarthritis, whereas AMPK activation has been shown to promote mitochondrial biogenesis and enhance oxidative metabolism under inflammatory conditions." (PMID 40427394, 2025). "Inhibition of the PI3K-Akt/mTOR pathway decreases inflammatory response in rats with osteoarthritis, and genetic mutations in the pathways have been associated with susceptibility to knee osteoarthritis in humans." (PMID 36518098, 2022). "mTOR activation and signalling have been implicated in bone biology in several in vivo studies, which implicated the activity of mTOR complexes in osteogenesis, skeletal growth and formation, chondral tissue development and osteoarthritis in mice." (PMID 34639180, 2021). "Curcumin, used in Indian and Chinese medicine as a wound-healing agent, among other uses, can also have a beneficial effect on osteoarthritis by possibly enhancing autophagy and reducing cell death and cartilage loss via Akt/mTOR signaling." (PMID 33809718, 2021). "Collectively, these findings suggest that suppressing the activation of the mTOR signaling axis could potentially reduce cellular senescence and mitigate osteoarthritis-associated chondrocyte catabolism, promoting an anabolic phenotype." (PMID 38407978, 2024). "Moreover, AMPK regulates mitochondrial function through the mammalian target of rapamycin (mTOR), a critical regulator of cell growth and metabolism, closely associated with inflammation and autophagy in osteoarthritis." (PMID 34876884, 2021). "mTOR signaling has also been linked to other bone-related diseases like osteoarthritis (OA)." (PMID 29445126, 2018). "Further insights into BBR's mechanism suggest that its protective impact on POCD may be linked predominantly to the inhibition of the PI3K/AKT/mTOR pathway, a pathway that has been implicated in a variety of disease states including acute lung injury, osteoarthritis and ischaemic diseases." (PMID 40735856, 2025). "Emerging frontiers indicate a growing focus on the role of mTOR signaling and cell death mechanisms in osteoarthritis." (PMID 40988280, 2025). "In osteoarthritis, miR-100-5p carried by MSCs–Exos can target and inhibit mTOR luciferase activity, thereby suppressing mTOR signaling and protecting articular cartilage." (PMID 39595531, 2024). "This further supports the notion that F-MSCs-Exo can deliver miR-146b-5p to the rat knee joint, silence TRAF6, and subsequently inhibit the PI3K/AKT/mTOR pathway to protect chondrocytes in osteoarthritis." (PMID 38105181, 2023). "In osteoarthritis, many natural products were found to attenuate cartilage degeneration and osteoarthritis progression via regulating AMPK/mTOR pathway, such as metformin, active vitamin D and sinensetin." (PMID 37249294, 2023). "We assumed that ALA‐24A exhibited its protective role against osteoarthritis by regulating AMPK/mTOR pathway." (PMID 37249294, 2023). "Several studies have confirmed that the mTOR signalling pathway plays an important role in various degenerative diseases, including osteoarthritis, diabetes, atherosclerosis, and Parkinson's disease." (PMID 36193577, 2023). "The antagonism of PI3K/AKT/mTOR signalling has also been reported to promote autophagy of articular chondrocytes and attenuate the inflammatory response in rats with osteoarthritis." (PMID 36869852, 2023). "It has been found that the autophagy level of chondrocytes in osteoarthritis rats can be increased by inhibiting PI3K/AKT/mTOR signal pathway, thus reducing the inflammation of the body." (PMID 36474568, 2022).